CASP8 (caspase 8)
Diseases named in the same sentence as CASP8 in open-access papers (continued):
Sharing a sentence is not in itself a finding about the gene and the disease.
neurodegenerative disease (12 papers, 2010 to 2024). A disorder of the central nervous system characterized by gradual and progressive loss of neural tissue and neurologic function. "As caspase inhibition has been proposed as a mechanism for AD treatment, our finding that AD-associated CASP8 variants reduce caspase function calls for caution and is an impetus for further studies on the role of caspases in AD and other neurodegenerative diseases." (PMID 28985224, 2017). "In human neurodegenerative diseases, inhibition of caspase-8 favors necroptosis by preventing cleavage and inactivation of RIPK1." (PMID 34753914, 2021). "Caspases are crucial mediators of neuronal death in a number of neurodegenerative diseases, and caspase 8 is considered a major therapeutic target in the context of AD." (PMID 32365525, 2020). "Surprisingly, unlike other antidepressants, we found that the standardized herbal medicine, Nelumbinis Semen, is free of factors that can induce neurodegenerative diseases such as caspase 8, α-synuclein, and amyloid precursor protein." (PMID 21118505, 2010). "Caspase-8 inactivation in brain tissue promotes necroptosis in human neurodegenerative diseases." (PMID 34753914, 2021). "Thus, blocking the activity of caspase 8 is considered a potential therapy for neurodegenerative diseases." (PMID 31083628, 2019).
inflammation (3 papers, 2020 to 2022). Aberrant reaction of the microcirculation characterized by movement of fluid and leukocytes from the blood into extravascular tissues. "Altogether, the sole deletion of Casp8 in ECs promoted early immune cell activation in the intestine with the subsequent progression to features of chronic intestinal inflammation (reminiscent of IBD in humans)." (PMID 35491615, 2022).
kidney disease (3 papers, 2017 to 2025). "In patients with kidney disease, apoptosis and necrosis are important in the pathogenesis of many different kidney diseases, but undoubtedly, Casp-8 is also involved in cellular processes concerning CVD patients with lipid disorders." (PMID 40149873, 2025). "We also found, using the Olink proteomic platform, that TNF-α and TMAO enhanced the secretion of additional inflammatory-and growth mediators associated with kidney disease; VEGFA, GDNF, CDCP1, OPG, uPA, AXIN1, MMP-1, MMP-10, PD-L1, HGF, Flt3L, 4E-BP1, CD40, CASP-8, ADA, TNFRSF9, TWEAK44–61." (PMID 38643262, 2024). "The analysis in biopsy-proven LN patients with active renal disease revealed elevated protein levels of CSF1, sIL15RA, sCD40, sCX3CL1, caspase 8, sIL18R1, bNGF, and GDNF compared to those without LN." (PMID 29026368, 2017). "When LN patients with active renal disease was compared to inactive LN subgroup, elevation of sIL15RA, CSF1, bNGF, sIL18R1, sCD40, sCX3CL1, and caspase 8 (P < 0.05), but not GDNF, in active LN patients was observed." (PMID 29026368, 2017). "Our serum protein analysis in LN patients with active renal disease revealed upregulated levels of CSF1, sIL15RA, sCD40, sCX3CL1, caspase 8, sIL18R1, bNGF, and GDNF compared to those without LN." (PMID 29026368, 2017).
metabolic disorders (3 papers, 2023 to 2025). "A large body of evidence places RIPK1/3-driven caspase-8 or MLKL signaling upstream of NLRP3 inflammasome activity in a range of disease settings, yet their contribution to inflammasome activity in metabolic disease is less clear." (PMID 39532538, 2025).
nervous system diseases (3 papers, 2016 to 2025). "Bryostatin 1, identified as an inhibitor of CASP8, has been confirmed to have therapeutic potential for various neurological disorders." (PMID 39038939, 2024).
adenocarcinoma (2 papers, 2017 to 2023). A common cancer characterized by the presence of malignant glandular cells. "The CASP8 expression level was found to be the highest in adenocarcinoma." (PMID 36533709, 2023).
head/neck tumors (1 paper, 2017). "Finally, two different cell death regulators, CASP8 and DIDO1, were often mutated in head/neck tumors that had higher lymphocyte infiltrates." (PMID 28749946, 2017).
hematologic malignancies (1 paper, 2025). "Notably, several drug-gene pairs—including those targeting CASP8, CASP10, KCNQ1, and HSPA8—are not currently approved nor under clinical evaluation for LN, representing investigational candidates with potential for future development in hematologic malignancies." (PMID 40883272, 2025).
CASP8 also shares sentences with these, for which no sentence is quoted: Cirrhosis (4 papers); rectal cancer (4); astrocytoma (3); B-cell lymphoma (3); cerebral infarction (3); gynecological tumors (3); Insulin resistance (3); lung fibrosis (3); atopic dermatitis (2); Bladder Urothelial Carcinoma (2); breast adenocarcinoma (2); carcinoma in situ (2); chronic periodontitis (2); colorectal tumor (2); heart diseases (2); Huntington disease (2); Lynch syndrome (2); papillary renal cell carcinoma (2); Shock (2); toxoplasmosis (2); uterine cancer (2); X-linked lymphoproliferative syndrome (2); Acidosis (1); adrenal cortical carcinoma (1); alcoholic liver diseases (1); Allergy (1); anencephaly (1); Angelman syndrome (1); ataxia telangiectasia (1); Atherosclerotic lesion (1).
A further 94 diseases each share a sentence with CASP8 in 1 paper.